STK11 (serine/threonine kinase 11)
Diseases named in the same sentence as STK11 in open-access papers (continued):
Sharing a sentence is not in itself a finding about the gene and the disease.
lung cancer (continued). "LKB1 (also known as STK11) has emerged as a major tumor suppressor in diverse malignancies, particularly melanoma, cervical cancer, and lung cancer." (PMID 24086281, 2013). "These molecules include ezrin (an intracellular protein necessary for the survival of osteosarcoma cells in the lung) and serine-threonine kinase 11 (STK11, or LKB1, a metastasis suppressor which regulates NEDD9 in lung cancer)." (PMID 22481931, 2012). "PTP4A1 is overexpressed in STK11-mutant NSCLC, but the functional impact of PTP4A1 in lung cancer is so far unknown." (PMID 39995872, 2025). "For example, in non–small cell lung cancer (NSCLC) tissue and/or circulating tumor DNA, STK11 and KRAS alterations frequently occur together, and STK11 variants, especially when coupled with pathogenic KRAS variants, can lead to resistance against immunotherapy in these cancers." (PMID 40860288, 2025). "Furthermore, in A549 lung cancer cells, which are STK11-mutant, addback of wildtype LKB1 was sufficient to reduce PER1 levels." (PMID 40715535, 2025). "A study using CRISPR/Cas9 technology to compare the effects of STK11 and PTEN on lung cancer development confirmed that mutations in STK11, but not PTEN, promote the progression of KrasG12D mutation lung adenocarcinomas." (PMID 38275900, 2024). "CDKN2A/B, STK11, and KEAP1 had a high frequency of alterations in lung cancer BMs cases." (PMID 37384291, 2023). "In the current study, we found that in STK11 mutant lung cancer without LKB1 expression, AXIN-1 served as a platform for binding with STING, which was enhanced by metformin treatment." (PMID 35281267, 2022). "Although STK11 is suggested to have roles in DNA repair pathways, the full extent of the influence of STK11 downregulation on DNA repair, pathways in lung cancer have not yet been explored." (PMID 36430528, 2022). "STK11/LKB1-mutant lung cancers are currently treated with radiotherapy with or without chemotherapy." (PMID 35165542, 2022). "In view of the critical role of EGFR and STK11 mutations in the efficacy of lung cancer treatment, we analyzed the differences of BMP5 mRNA expression in patients with and without EGFR and STK11 mutations." (PMID 34745928, 2021). "Whereas STK11/LKB1 loss alone was not sufficient to trigger oncogenesis, STK11 inactivation in a mutant KRAS-driven model of mouse lung cancer strongly stimulated growth and metastasis." (PMID 34831355, 2021). "In a more focused comparison with the most frequent neuroendocrine type of lung cancer, SCLC, type I LCNECs with STK11 and KEAP1 alterations exhibited a high degree of similarity with these carcinomas, as well as high expression of neuroendocrine genes and a profile of ASCL1high/DLL3high/NOTCHlow." (PMID 29535388, 2018). "Lung cancer A549 cells with defective STK11 (Q37*) (data not shown) or cell lines with STK11 knockdown showed undetectable effect on pAMPK when treated with palbociclib." (PMID 28205554, 2017). "In lung cancer, a short STK11 isoform lacking the 124 N-terminal amino acids has recently been described as an oncogene." (PMID 26625312, 2017). "With 269 novel interactions, OncoPPi greatly expands the landscape of interactions among this selected set of lung cancer genes and defines interactions with potential significance for cancer PPI target discovery, such as CDK4/STK11, LATS2/RASSF1 and MYC/NSD3 (WHSC1L1)." (PMID 28205554, 2017).
lung cancer (continued). "Furthermore, TMB was not affected by STK11 mutations; and in fact, it was even elevated in tumors with mutant KEAP1 according to our analysis of the MSK lung cancer dataset." (PMID 41378285, 2025). "STK11 and KEAP1 mutations do not seem to influence the prognosis in KRAS wildtype lung cancers." (PMID 38067288, 2023). "One study has reported STK11 F354L in lung cancers, but not in healthy tissue." (PMID 35621648, 2022). "However, regardless of TMB and PD-L1 status, the presence of STK11/LKB1 and KEAP1 mutations is a poor prognosis factor in lung cancer." (PMID 35407463, 2022). "In the old lung cancer group, there were genes significantly concurrent with actionable driver genes (CDKN2A, NF1): FAT1, LRP1B, ARID2 with CDKN2A; EPHB1 with NF1, and genes significantly exclusive with actionable driver genes (EGFR, KRAS): MLL2, STK11, KRAS with EGFR." (PMID 35096611, 2021). "As for the genetic landscape in detail, several incidences of mutated genes that were adverse to prognosis were observed to be lower in the young lung cancer group (LRP1B, SMARCA4, STK11, FAT2, RBM10, FANCM), which may explain the better prognosis of the young lung cancer group to some extent." (PMID 35096611, 2021).
lung adenocarcinoma (304 papers, 2007 to 2026). A carcinoma that arises from the lung and is characterized by the presence of malignant glandular epithelial cells. "This study investigates the mutational landscape and clinical characteristics of STK11-mutated lung adenocarcinomas." (PMID 41549133, 2026). "A key feature of KEAP1-mutant lung adenocarcinoma is its frequent co-occurrence with STK11 mutations." (PMID 41541668, 2026). "Approximately 8% of lung adenocarcinomas have concomitant STK11 loss and KRAS mutation, which confers a particularly poor prognosis." (PMID 40069402, 2025). "For example, glycolysis is critically involved in lung adenocarcinomas (LUADs) with STK11/LKB1 mutations, key genomic drivers of primary resistance in KRAS-mutated tumors." (PMID 39941865, 2025). "The other immune checkpoint inhibitor naïve NSCLC patient, who had PD on study treatment, had a KRAS/STK11-mutated PD-L1-negative lung adenocarcinoma." (PMID 41523436, 2025). "A549 (STK11 deficient/KRAS mutant lung adenocarcinoma) cells again demonstrate increased glycolysis and increased HIF1α expression in normoxia, both of which are reduced with either STK11 re-expression or rapamycin treatment." (PMID 40069402, 2025). "In fact, STK11 mutations are among the most frequent drivers of ICI resistance in KRAS-mutant lung adenocarcinoma." (PMID 41051525, 2025). "STK11/LKB1 inactivating mutations often cooccur with KRAS-activating mutations, and STK11/LKB1 inactivating mutations are also a driver of primary resistance to immunotherapy in KRAS-mutant lung adenocarcinoma (LUAD)." (PMID 40612109, 2025). "The associated metabolic re-wiring of STK11 deficiency in lung adenocarcinoma appears to represent a limited therapeutic vulnerability." (PMID 40069402, 2025). "STK11/LKB1 co-mutations are frequent in KRASG12C mutant lung adenocarcinomas, and LKB1 is a regulator of chromatin accessibility linked with cellular plasticity." (PMID 39301544, 2024). "Serine/threonine kinase 11 (STK11), a tumor suppressor gene, exhibits frequent mutations in lung adenocarcinoma (LUAD)." (PMID 38205151, 2024). "Serine Threonine Kinase 11 (STK11) loss of function (LoF) correlates with anti-PD-1 therapy resistance in patients with KRAS-driven lung adenocarcinoma (LUAD)." (PMID 37968341, 2024). "As STK11/LKB1 mutations occur in approximately one-third of KRAS-mutated lung adenocarcinomas, to uncover the potential mechanism is in high demand and is critical for developing effective combination strategies." (PMID 38291516, 2024). "Most notably, alterations of STK11/LKB1 in the presence of KRAS mutations have been linked to primary resistance to PD-1 inhibitors in lung adenocarcinoma patients undergoing chemoimmunotherapy." (PMID 38903504, 2024). "The LKB1/STK11 tumour suppressor is mutated in ∼ 30% of NSCLCs, typically lung adenocarcinomas (LUAD)." (PMID 39048991, 2024). "STK11/LKB1 mutations are considered to be associated with PD-1 inhibitor resistance in KRAS-mutant lung adenocarcinoma." (PMID 38366663, 2024). "Inactivating mutation of the tumor suppressor STK11/LKB1 is one of the genomic drivers of KRAS-mutated lung adenocarcinoma." (PMID 38233872, 2024). "STK11/LKB1 mutations have been found to cause primary resistance to PD-1/PD-L1 inhibitors in patients with KRAS-mutated lung adenocarcinoma." (PMID 36675641, 2023). "Somatic mutations in LKB1, encoded by serine/threonine kinase 11 (STK11), occur in approximately 20-25% of lung adenocarcinoma (LUAD), while inactivating mutations in KEAP1 are observed in approximately 10-15% of LUAD." (PMID 37675220, 2023). "For instance, the inactivation of the STK11 tumor suppressor gene in KRAS-mutated lung adenocarcinoma shifts the TME towards immunosuppressive neutrophils and reduced expression of PD-L1." (PMID 37444584, 2023). "In the context of the TME, glutaminase inhibition contrarily impaired CD8+ T-cell activation in STK11-/Lkb1-deficient models of lung adenocarcinoma." (PMID 37180129, 2023).
lung adenocarcinoma (continued). "This study attempted to unveil how mutated STK11 impact the differentiation of macrophages in lung adenocarcinoma (LUAD)." (PMID 37506141, 2023). "For example, in melanoma, mutations in JAK1/JAK2 (Janus Kinase 1/2) and B2M (beta-2-microglobulin) genes associated with acquired resistance to ICIs, and STK11/LKB1 mutations in KRAS mutated lung adenocarcinoma, have been documented." (PMID 38136385, 2023). "EGFR, KRAS, and STK11 genes are known to be mutated in lung adenocarcinoma with a high frequency as well as ERBB2 with a lower frequency." (PMID 36499466, 2022). "Skoulidis and colleagues showed that Lkb1/Stk11 loss promoted PD-1/PD-L1 inhibitor resistance, using Kras- mutant murine lung adenocarcinoma models." (PMID 35055413, 2022). "Lung adenocarcinomas showing STK11/LKB1 defects, often in association with an altered KRAS, show poor response to immunotherapy." (PMID 36428727, 2022). "STK11/LKB1 alterations were also significantly associated with PD-L1–negative status in lung adenocarcinomas with intermediate to high TMB." (PMID 35703181, 2022). "This literature review depicts the association of STK11/LKB1 gene mutations and lung adenocarcinoma." (PMID 35165542, 2022). "STK11/LKB1 mutations are more prevalent in lung adenocarcinomas but are also found in pulmonary squamous cell carcinoma and large cell adenocarcinoma." (PMID 35165542, 2022). "For example, in 230 cases of lung adenocarcinoma in The Cancer Genome Atlas, STK11 was either deleted or mutated in 43 (19%) and PRKAA1 was amplified in 22 (10%)." (PMID 36383046, 2022). "In contrast, loss of Stk11 drive tumor progression and is often found mutated in human samples of lung adenocarcinoma." (PMID 33652656, 2021). "It was recently demonstrated that NRF2 activation acts as a critical oncogenic driver, and can promote aggressive lung adenocarcinoma by cooperating with STK11 loss and KRAS activation." (PMID 33572782, 2021). "Our study revealed that loss of Stk11 drives lung adenocarcinoma progression, whereas Pten is dispensable." (PMID 33652656, 2021). "Serine/Threonine Kinase 11 (STK11) encodes an important tumor suppressor that is frequently mutated in lung adenocarcinoma." (PMID 34849607, 2021). "Somatic STK11 mutations arise preferentially in lung adenocarcinoma where they have been detected in up to 30% of cases." (PMID 34142658, 2021). "Each of the 28 variant STK11 cDNAs were expressed in STK11 null A549 lung adenocarcinoma cells and expression verified by western blot (available at Carcinogenesis Online)." (PMID 34849607, 2021). "Concurrent mutations in STK11/KEAP1 act as a major driver in primary resistance to PD1 blockade in KRAS-mutated lung adenocarcinoma." (PMID 34204917, 2021). "The results also highly indicate the possibility of STK11 gene mutation as a prognostic indicator of anti-PD-1/PD-L1 therapy in lung adenocarcinoma." (PMID 33633793, 2021).
lung adenocarcinoma (continued). "LKB1 activity is lost in a wide spectrum of human cancers and the gene that encodes LKB1 (STK11) is the third most frequently mutated tumor suppressor in human lung adenocarcinoma." (PMID 33514834, 2021). "Overall, by using the CRISPR/Cas9 mouse model of lung adenocarcinoma, we showed that mutations in Stk11 are a key driver, whereas loss of Pten is dispensable for adenocarcinoma progression." (PMID 33652656, 2021). "STK11/LKB1 mutation has been identified as a main driver of anti-PD1 resistance in KRAS-mutant lung adenocarcinoma, and loss of LKB1 has been linked to decreased numbers and function of T cells in the TME." (PMID 33013881, 2020). "One unexpected observation was that normal lung and lung adenocarcinomas had similar levels of STK11 hotspot mutations." (PMID 32940377, 2020). "Other important pathways for resistance include STK11/LKB1 mutation in KRAS mutant lung adenocarcinoma that has been shown to directly induce resistance to ICI therapy, with a significant decrease in the response rate and overall survival." (PMID 35582715, 2019). "Some genes significantly mutated were exclusively mutated in lung adenocarcinoma, such as STK11 (LKB1), RBM10, KEAP1, RIT1 and MET, while other genes such as NFE2L2, KDM6A, RASA1, NOTCH1 and HRAS are significantly mutated in LSQCC." (PMID 30060526, 2018). "KRAS mutations in lung adenocarcinoma were also reported to be associated with co-mutations in STK11/LKB1 (the KL subgroup)." (PMID 29486723, 2018). "STK11 mutation is known to induce p21 expression predominantly in lung adenocarcinoma, and our observation from the western blot analysis indicate high levels of p21 expression in 10/11 (91%) cTCL tumors." (PMID 29854308, 2018). "The combined splice site region of STK11 covers 36 bps and is mutated in four lung adenocarcinoma (LUAD) cancer samples, which is approximately 56 times more mutations than expected under the null model." (PMID 28362259, 2017). "As befitting a tumour suppressor, the STK11 gene encoding LKB1 is often mutated or deleted in cancers (note the preponderance of green and blue bars), particularly in lung adenocarcinomas where mutations occur in 15–20% of cases." (PMID 26934201, 2016). "The proximal-proliferative subtype in lung adenocarcinoma is characterized by an enrichment of mutations in KRAS along with inactivation mutations in STK11." (PMID 25405470, 2014). "Additionally, STK11/LKB1 mutations cause resistance to PD-1 blockade in KRAS-mutated lung adenocarcinoma.The reduced antigen-presenting ability of tumor cells is characterized by abnormalities in MHC molecules." (PMID 41293265, 2025). "Thus, lung adenocarcinomas with loss or inactivation of STK11 have low AMPK activation and high mTOR activity." (PMID 40069402, 2025). "For example, GLS inhibition with CB-839 negatively impacted immune activation by the anti-PD1 immunotherapy in the transgenic murine models of KRAS/Serine-threonine kinase 11 (STK11)-mutant lung adenocarcinoma carrying an immune suppressive mutation in the STK11 gene." (PMID 39199642, 2024). "In patient samples, STK11 function is often altered either by inactivating point mutations, reduced gene expression or chromosomal loss in 4–34% of tested human adenocarcinomas of the lung, with the percentage of somatic mutations being described as lowest in Asian cohorts and highest in Caucasians." (PMID 35621648, 2022).